CD4 (CD4 molecule)
Diseases named in the same sentence as CD4 in open-access papers (continued):
Sharing a sentence is not in itself a finding about the gene and the disease.
tumor (continued). "CD4+ T cells play an essential role in initiating anti-tumor immune responses by activating CD8+ cytotoxic lymphocytes, the primary cells responsible for targeting and destroying tumor cells." (PMID 40918463, 2025). "In this study, we presented strong evidence that such a replication-defective ΔM062R MYXV can enhance immunotherapy for OC and alleviate ovarian TAM immunosuppression of DC-stimulated tumor antigen-specific human CD4+ T cell responses." (PMID 40872773, 2025). "TGFB facilitates the conversion of naive CD4+ T cells into CD4+Foxp3+ regulatory T-cells (Tregs), which inhibit anti-tumor immunity, thereby promoting tumor progression." (PMID 40565031, 2025). "It is an important immunomodulatory protein that enhances the production of interferon-gamma (IFN-γ) by tumor antigen-specific CD4+ T cells, which in turn strengthens the cytotoxic function of CD8+ T cells, ultimately inhibiting tumor growth." (PMID 41445755, 2025). "T-cell sequestration in GBM is caused by the tumor-induced loss of S1P1 from T-cell surfaces, both CD4+ and CD8+." (PMID 40514725, 2025). "Robust upregulation of 4-1BB within CD8+ TILs and OX40 upregulation within CD4+ TIL upon co-culture with autologous tumor digests were observed." (PMID 40806287, 2025). "Collectively, pseudohypoxia induced by HIF-PH inhibitors enhances the tumor immune response via IL-2 induction by CD4+ T cells in the spleen and TME." (PMID 40343532, 2025). "In glioblastoma, however, the anti-tumor response is compromised since CD4+/CD8+ T-cells constitute only 2% of infiltrating immune cells." (PMID 41208963, 2025). "This anti-tumor activity was partially abrogated by depletion of CD4 and CD8 T cells, and completely abrogated by depletion of NK cells, resulting in a decreased OS of treated mice." (PMID 40315226, 2025). "TAGAP overexpression or silencing was employed to assess its impact on cytokines production and differentiation of CD4+ T cells, downstream c-Rel expression, and tumor progression." (PMID 39998561, 2025). "Flow cytometry analysis revealed a significant increase in the percentage of CD3+CD8+ and CD3+CD4+ T cells in tumor-DLNs and spleen in combined treatment mice." (PMID 40386771, 2025). "First, cytotoxic CD4+ T cells are the dominant CD4+ population in blood, sharing specificity with tumor-resident CD4+ cells despite being the minority of total CD4+ cells." (PMID 40299576, 2025). "The RCOR2/LSD1 sub-axis suppresses RNF43 transcription to activate Wnt/β-catenin signaling in tumor cells, whereas the RCOR2/HDAC1/2 sub-axis inhibits CIITA and MHC-II expression in tumor cells to block activation of CD4+ and CD8+ T cells." (PMID 40608411, 2025). "Depletion of B cells, or conditional knockout ICOSL in B cells, reduced this tumor response to doxorubicin treatment and correlated with reduced CD4 and CD8 effector cells and increased Treg cells." (PMID 40356924, 2025). "The expression of PD-L1 and the tumor microenvironment markers (CD4, CD8, CD68, and CD163) were examined in LSCC using immunohistochemistry." (PMID 40429363, 2025). "CD4+ T cells secrete proinflammatory cytokines and chemokines to recruit other immune cells, and can kill tumour cells using an MHC II‐dependent mechanism." (PMID 39462771, 2025). "A second validation analysis using single‐cell RNA‐seq data from paired blood–tumor samples showed that CD4+ T cell expression in blood and in tumor cells also had a high correlation (r = 0.93)." (PMID 41216857, 2025). "Specifically, we found that CD8+ T cells promoted homing of CD4+Foxp3+ Tregs to the tumor bed by increasing the levels of CCR5 chemokines in the tumor microenvironment in an IFN-γ– and TNF-α–dependent manner." (PMID 40553564, 2025). "Follicular helper T cells (Tfh), a subset of CD4+ T cells, support B cell proliferation and differentiation, enhancing anti-tumor immune responses." (PMID 40149517, 2025).
tumor (continued). "Further, the macrophages M2, Tregs, CD4 T and B cells were higher in the tumours with high ST6GALNAC1 expression." (PMID 41152402, 2025). "We found that TGFB1/EGFR, LTA/LTBR, CD46/JAG1, and AREG/EGFR ligand‐receptor pairs were stronger in CD4+ T cell‐Plac1+ tumor cells than in CD4+ T cell‐Plac1− tumor cells, among which LTA/LTBR expression was highly specific for Tregs and Plac1+ cells." (PMID 40056047, 2025). "This patient had the residual tumor scar inside the nose resected almost a year after treatment initiation, and the pathology report revealed normal tissue highly inflamed by CD4+ T cells but also with increased CD8+ T cell infiltration." (PMID 40107242, 2025). "Like CD4+ T cells, DCs also play crucial roles in both tumor-specific CD8+ T cell activation phases." (PMID 41030446, 2025). "CD4+ T cells, which produce cytokines that generate a durable immune response to eliminate pathogens or tumor cells, are primarily referred to as “helper T cells”." (PMID 40756366, 2025). "They gain the function of inducing naïve CD4+ cells to become regulatory T-cells (Tregs) and support the tumor's immune evasion." (PMID 40523922, 2025). "In terms of detailed inhibitory receptor expression analysis, significantly higher fractions of tumor-infiltrated CD4+ T cells expressed LAG-3 (13.06 ± 4.63% of CD4+ T cells) and PD-1 (14.01 ± 3.76% of CD4+ T cells)." (PMID 41221283, 2025). "The help from CD4+ T cell–derived IL-2 in the tumor milieu is required for the full response of CD8+ cytotoxic T cells." (PMID 40759573, 2025). "Activated B cells also play a critical role by inducing Th1-type CD4+ T cell responses, working synergistically to bolster tumor immune responses." (PMID 39859524, 2025). "Activated CD4 T cells play a key role in tumor immunity by producing cytokines that activate M1 macrophages and enhance CD8+ T-cell cytotoxicity." (PMID 41228276, 2025). "Consistently, tumor-infiltrating lymphoid subsets such as B cells, CD4+ T cells, CD8+ T cells, immature NK cells, mature NK cells, and NKT cells were significantly reduced in advanced iCCA tumors." (PMID 41459487, 2025). "PD-1+CD4+Foxp3− cells contribute to tumor immune evasion, as they accumulate intratumorally during tumor progression and limit effector CD8+ T cell functions." (PMID 40281508, 2025). "Ten cell types were identified, namely B cell, CD4 T cell, dendritic cell (DC), endothelial cell, epithelial cell, fibroblast, macrophage, neutrophil, plasma cell, and tumor cell." (PMID 41583431, 2025). "By correcting the age–related defects in dendritic cells, the ability of CD4 T cells to kill tumor cells can be enhanced." (PMID 40547923, 2025). "Tumor samples were evaluated using immunohistochemistry (IHC) to assess CD4+ and FOXP3+ TILs in intratumoral and stromal regions." (PMID 41007768, 2025). "The immune cells infiltrating the TME, such as dendritic cells (DCs), Treg cells and CD4+ T cells, have been proved to be related to the immune escape of tumor cells." (PMID 40296917, 2025). "Immune infiltration analysis indicated that macrophages, CD4 T cells, and T helper cells accounted for over 50% of the tumor tissue composition." (PMID 40475759, 2025). "Inhibiting CD4+ T-lymphocyte activation and proliferation can further inhibit anti-tumor immune response." (PMID 40417009, 2025). "Our findings showed that CD4+ Tregs were more abundant in tumor samples and metastatic lymph nodes than in adjacent tissues and normal lymph nodes, implying the potential role of CD4+ Tregs in facilitating lymph node metastasis in ESCC." (PMID 39741182, 2025). "These engagers can be composed of a TCR or TCR-like domain that binds to a neoantigen-HLA complex and a domain that binds to CD3, thereby stimulating and redirecting CD8 as well CD4 T cell reactivity towards tumor cells." (PMID 40151616, 2025).
tumor (continued). "For example, CD4+ T cells can recognize tumor-specific antigens and indirectly kill tumor cells by activating other immune cells, such as macrophages and natural killer (NK) cells." (PMID 40936903, 2025). "CD8 T cells primarily target virus-infected or tumor cells, whereas CD4 T cells coordinate immune responses by activating cytotoxic T cells, B cells, and aspects of the innate immune system." (PMID 40544271, 2025). "In contrast with the case of young mice, substantial increases in B220+ B cells and CD8+ and CD4+ T cells were detected in bronchoalveolar lavage fluid (BALF) of tumor-bearing aged mice, particularly when they were treated with anti–PD-L1 therapy." (PMID 40198121, 2025). "Fingolimod itself has many side effects, including suppression of migration and activation of CD8+ and CD4+ T cells, which prevents effective tumor cell infiltration and killing." (PMID 40332322, 2025). "Evidence suggests that B7-H3 contributes to the inhibition of CD8 T-cell anti-tumor activity across multiple malignancies, with some research implicating its role in regulating CD4 T-cell functions." (PMID 40801642, 2025). "Compared to tumors with diploid/normal copy number, levels of B cell and CD4+ T cell infiltration were reduced in tumor samples with arm-level deletion of BTLA, CLDN11, and FGF5." (PMID 39796775, 2025). "In terms of cancer immune-related features, the ER signature score was positively correlated with and infiltration levels of anti-tumor immune-associated cells in SKCM, such as CD4 T cells and CD8 T cells." (PMID 41431699, 2025). "Functionally, IFN-γ contributes to the maintenance of tumor cells in a state of equilibrium, as antibody-mediated neutralization of IFN-γ phenocopied CD4 T-cell depletion, accelerating tumor escape in triple combination–treated mice." (PMID 40299790, 2025). "Cancer vaccines are designed to deliver tumour antigens or their genes to APCs, which, when processed, activate anti-cancer cytotoxic T-cell and helper T-cell (CD4+ cells) responses and produce immune memory to provide long term anti-cancer action." (PMID 40943226, 2025). "Studies have shown that CD4 + CAR-T cells can activate antigen-presenting cells to enhance endogenous anti-tumor immunity, while CD8 + CAR-T cells maintain long-term memory responses." (PMID 40604935, 2025). "Significant correlation was observed between DGAT1 expression levels and tumor-infiltrating CD4+ T lymphocyte density." (PMID 40554491, 2025). "E743–77-pulsed bm12 mBMDCs generate allogeneic CD4+ T cell responses through allogeneic MHC class II to support E7 peptide–dependent CD8+ T cell responses in TC-1 tumor–bearing mice." (PMID 40857404, 2025). "Particularly, patients with larger tumor sizes exhibit significantly higher Gal-9 expression levels on CD4+ T cells." (PMID 39958335, 2025). "We also found that hub genes were highly expressed in tumor tissues, while B cells, CD4+, and CD8+ T cells pretended to be positive among the hub gene–negative cohort." (PMID 40469997, 2025). "In this study, CD4+ T cells arrested in DCs only when cognate tumor antigens were presented via MHC class II." (PMID 40257446, 2025). "T cells mainly include CD8 and CD4 T cells, which can receive antigen presentation from dendritic cells, inducing tumor-specific responses." (PMID 40224547, 2025). "The cellular and molecular results have further shown an altered tumor immune microenvironment from suppressive to active by stimulating the infiltration of CD4+, CD8+ T-cells, and NK cells, as well as decreasing immunosuppressive cells." (PMID 40805151, 2025). "The increases macrophage secretion of CX3CL1, recruiting CD4+ T cells and NK cells to tumor sites and enhancing anti-tumor responses." (PMID 41417432, 2025). "A study found that CTLA-4 on Tregs interacted with CD80 expressed on dendritic cells within the lymph nodes surrounding the tumor to regulate CD4+ T cell infiltration into tumors." (PMID 40861801, 2025).
tumor (continued). "While we would anticipate that CD80 and CD86 would have a positive impact on anti-tumor immunity, we demonstrate that blockade of CD80 and CD86 signaling limits CD4 infiltrates in tumors and prevents the Treg expansion caused by radiation treatment." (PMID 41417245, 2025). "These HSP-Exs are able to more efficiently induce the phenotype and function of DCs, as well as CD8+ and CD4+ T-cells, to reach a mature state, which is essential for triggering tumor rejection." (PMID 39911383, 2025). "As expected, both CD8 and CD4 T cells often expressed multiples of these three activation markers at the same time in the tumor." (PMID 39918475, 2025). "Upon engagement with gp100-expressing tumor cells, tebentafusp facilitates the recruitment of both CD4+ and CD8+ T lymphocytes, resulting in T cell activation, pro-inflammatory cytokine production, and tumor cell lysis." (PMID 40725830, 2025). "More robust rescue of RCOR2-KO1 tumors was observed in the MC38 tumor mouse model when mice were cotreated with anti-CD4/CD8 antibodies." (PMID 40608411, 2025). "In summary, our findings show that both Ad‐CIITA and Ad‐CIITA mutant enhance the immunogenicity of GB for allogenic T‐cells, facilitating efficient tumor cell killing in the presence of either CD4+ or CD8+ T‐cells." (PMID 39535369, 2025). "This Treg reduction was accompanied by increased infiltration of IFN-γ-producing CD8+ and CD4+ T cells, suggesting a more effective immune response against the tumor." (PMID 41394821, 2025). "CD4+ T cells are activated by tumor antigens presented by antigen-presenting cells (APCs) and produce cytokines such as IFN-γ and tumor necrosis factor-alpha (TNF-α), which in turn activate CD8+ CTLs and macrophages." (PMID 41007114, 2025). "Within the tumor microenvironment, tumor cells can recruit immunosuppressive cells, such as CD4+ T cells, which compromise the cytotoxic function of CD8+ T cells." (PMID 40356928, 2025). "Specifically, CD161 expression was positively associated with immunomodulators and tumor-infiltrating immune cells, especially CD8+T cells, CD4+T cells, and dendritic cells." (PMID 40115278, 2025). "Next, we explored the different CD4+ and CD8+ T-cell subsets in tumor infiltrates to identify potential differences associated with treatment response." (PMID 40897819, 2025). "Conversely, the low-PCD group primarily harbored early-stage naive and effector CD4+ T cells, implying a potentially more robust anti-tumor response." (PMID 40740783, 2025). "Apparently, the senescent-like state induced by RMC-7977 and palbociclib facilitates CD4 T cell–mediated surveillance of residual tumor cells upon the addition of the CD40 agonist." (PMID 40299790, 2025). "Recent studies have identified cytotoxic CD4+ T cells (activated TH1 cells) that directly kill tumor cells by releasing granzyme B and perforin." (PMID 40176817, 2025). "TIL analysis revealed a significant increase in CD4 + and CD8 + T cells and tumor-associated macrophages (P < 0.01) in the triple combination therapy group." (PMID 40836337, 2025). "It has been previously established that tumor inducible acquisition of CD4 and CD8 expression represents a polyfunctional subset of T cells within tumors that have undergone T cell receptor (TCR) stimulation." (PMID 41035646, 2025). "Flow cytometry analysis showed that chimera treatment exhibited a significant reduction in both the frequency and absolute number of FoxP3+CD4+ Treg cells per milligram of tumor tissue compared to the PBS control group." (PMID 41402667, 2025). "Another population of FAP+PDPN+ CAFs, which closely interacts with T cells at the tumor periphery, was shown to significantly suppress the proliferation of CD4+ and CD8+ T cells by secreting nitric oxide." (PMID 40890855, 2025). "For example, compared to the control group, activated CD4 + T cells were dramatically up-regulated in both CRC tumor samples and LUAD tumor samples (all P < 0.0001)." (PMID 40796704, 2025).
tumor (continued). "The expression of MCAM in BLCA was associated with tumor purity (r = − 0.302), CD8 + T cells (r = 0.218), CD4 + T cells (r = 0.111), macrophages (r = 0.352), neutrophils (r = 0.183), and dendritic cells (r = 0.183)." (PMID 41407823, 2025). "In patients with ductal carcinoma in situ (DCIS) treated with intralesional DCs, a tumor-specific CD4+ Th1 immune response was seen in the sentinel lymph node that correlated with a higher pCR rate." (PMID 40333343, 2025). "This region showed a greater infiltration of CD3+ and CD4+ lymphocytes than the center of the tumor, suggesting a robust immune response at the margins of the tumor." (PMID 40469283, 2025). "In oral RMS, studies have shown that high infiltration of CD4+ and CD8+ T cells into the tumor is associated with a better prognosis and improved patient outcomes." (PMID 41007114, 2025). "The body’s primary anti-tumor immune response relies on cellular immunity, where an elevated CD4+/CD8+ ratio indicates stronger anti-cancer immune capability, while a lower ratio suggests diminished immunity." (PMID 41446305, 2025). "The reduction of immunosuppressive myeloid cells allowed expansion and activation of anti-tumor CD4+ T cells which limited CRC metastasis formation." (PMID 41397968, 2025). "One possible explanation is that F1/F3 recruits T cells into the tumor and leverages CD4+ T cells to support and maintain CD8+ T-cell cytotoxicity." (PMID 40573908, 2025). "At the same time, tumor-infiltrating CD4+ and CD8+ T cells in primary PCa have been shown to express the immune checkpoint marker and ICI target PD-124." (PMID 41000797, 2025). "Given the importance of T cells in other tumour types as key immunotherapeutic targets, we also interrogated the positioning and proximity of both CD4+ and CD8+ T cells within NF2 SWN-related VS." (PMID 40140675, 2025). "During cancer, the blockade of PD-1 can restore the activity of tumor-infiltrating CD4 T cells demonstrating their local immune involvement and that immune checkpoint molecules control local reactivity." (PMID 39880819, 2025). "Instead, Postn-deficient tumors showed increased infiltration of CD4+ and CD8+ T cells and reduced proportions of immunosuppressive myeloid cells, including tumor-associated macrophages (TAM)." (PMID 41448855, 2025). "To validate the correlation of Plac1+ tumor cells with CD4+ T cells, we performed an IHC assay in the in‐house TMA cohort." (PMID 40056047, 2025). "TIM-3 is expressed on various immune cells, including CD4+ Th1, CD8+ CTL, IL-17-producing CD4+ effector cells (Th17), tumor-infiltrating T-cells (TILs), Tregs, and innate immune cells." (PMID 40281554, 2025). "DCs loaded with tumor antigens stimulate CD4+ T cell responses via peptide–MHC class II presentation and activate CD8+ T cells through the cross-presentation of MHC class I molecules." (PMID 41502522, 2025). "General cell counts of immune population within tumor-resident viable leukocytes revealed that F4/80+ macrophages and CD11c+ dendritic cells were the most abundant, followed by CD4+ and CD8+ lymphocytes, CD11b+ Ly6C+ monocytes and CD11b+ Ly6G+neutrophils." (PMID 41459512, 2025). "CD4+ T-helper 2 (Th2) cells predominantly secrete cytokines including IL-4, IL-5, IL-6, IL-10, and IL-13, which are known to suppress anti-tumor immune responses." (PMID 40432130, 2025). "Conventional dendritic cells type 2 (cDC2, CD11b+) were shown to present tumor-derived antigens to CD4+ T-cells, but then fail to support antitumor CD4+ T-cells differentiation." (PMID 40641916, 2025). "This formulation resulted in pronounced tumor regression and robust infiltration of CD4+/CD8+ T cells and natural killer (NK) cells, outperforming both free drug and PDT monotherapy." (PMID 41149218, 2025). "CD4+ T cells have more diverse repertoires, with lower frequencies of public clones; however, tumor-suppressive TCRs also have more homologous public clonotypes." (PMID 40650228, 2025).